XYLT1 (xylosyltransferase 1)
Description:
Catalyzes the first step in the biosynthesis of chondroitin sulfate and dermatan sulfate proteoglycans, such as DCN. Transfers D-xylose from UDP-D-xylose to specific serine residues of the core protein. Required for normal embryonic and postnatal skeleton development, especially of the long bones. Required for normal maturation of chondrocytes during bone development, and normal onset of ossification (By similarity).
Synonyms: XT-I; XylT-I; XT1; PXYLT1; DBQD2; XTI; XYLTI
Tractability: Small molecule: a structure with a bound ligand is known. Antibody: UniProt places it where antibodies can reach, with high confidence; UniProt predicts a signal peptide or a membrane-spanning region; its Gene Ontology location is reachable by antibodies, with medium confidence; the Human Protein Atlas places it where antibodies can reach. PROTAC: ubiquitination databases record sites on it; its protein half-life has been measured.
Gene: Protein-coding gene on chromosome 16 (17,101,769 to 17,470,960, reverse strand). Ensembl gene ENSG00000103489.
Subcellular location: Golgi apparatus membrane; Secreted
Subcellular location (Human Protein Atlas): Plasma membrane; Endoplasmic reticulum; Predicted to be secreted
Pathways (Reactome):
Metabolism: Glycosaminoglycan-protein linkage region biosynthesis
Gene Ontology:
Molecular function: protein xylosyltransferase activity; glycosyltransferase activity; UDP-glycosyltransferase activity
Biological process: chondroitin sulfate proteoglycan biosynthetic process; heparan sulfate proteoglycan biosynthetic process; proteoglycan biosynthetic process; embryonic skeletal system development; glycosaminoglycan biosynthetic process; glycosaminoglycan-protein linkage region biosynthetic process; ossification involved in bone maturation
Cellular component: extracellular region; Golgi apparatus; Golgi membrane; Golgi cis cisterna; membrane
Genetic constraint (gnomAD): Loss-of-function variants: 31 observed, 87.47 expected, observed/expected ratio (o/e) 0.35, 90% interval 0.26 to 0.48. The upper end of that interval is the gene's LOEUF score, 0.48, which puts it in group 2 of 6, group 1 being the genes least tolerant of losing a copy. Missense variants: 1,115 observed, 1,186.9 expected, observed/expected ratio (o/e) 0.94, 90% interval 0.89 to 0.99. Synonymous variants: 513 observed, 476.4 expected, observed/expected ratio (o/e) 1.08, 90% interval 1 to 1.16.
Homologues: Orthologues: chimpanzee XYLT1 (99% identical), macaque XYLT1 (98% identical), pig XYLT1 (94% identical), mouse Xylt1 (91% identical), rat Xylt1 (91% identical), guinea pig XYLT1 (86% identical), rabbit XYLT1 (78% identical), tropical clawed frog xylt1 (75% identical), zebrafish xylt1 (65% identical), Drosophila melanogaster oxt (33% identical), Caenorhabditis elegans sqv-6 (23% identical), Caenorhabditis elegans gly-16 (7% identical), and 16 more. Paralogues in human: XYLT2 (50% identical), WSCD2 (11% identical), GCNT1 (11% identical), GCNT4 (10% identical), WSCD1 (10% identical), GCNT3 (9% identical), GCNT2 (8% identical), GCNT7 (7% identical).
Diseases named in the same sentence as XYLT1 in open-access papers:
XYLT1 is named in the same sentence as 44 diseases in open-access papers, as found by Europe PMC text mining. Sharing a sentence is not in itself a finding about the gene and the disease. The quoted sentences say what the papers report.
Baratela-Scott syndrome (15 papers, 2014 to 2025). "Variants in XYLT1 have also been shown to contribute to disorders associated with developmental delay, such as Baratela-Scott syndrome (BSS)." (PMID 40386381, 2025). "XYLT1 is linked to Desbuquois dysplasia 2 (OMIM # 615777), an autosomal recessive skeletal disorder characterized by growth retardation, joint laxity, short extremities, progressive scoliosis, and developmental delay, in the absence of hand abnormalities." (PMID 36833424, 2023). "The phenotypes of this disorder are common to those of Desbuquois dysplasia type 2 caused by mutations in XYLT1." (PMID 34539746, 2021). "XYLT1 deficiency causes Desbuquois dysplasia type 2, a skeletal disorder comprising short stature, dislocation of the large joints, flat face and prominent eyes." (PMID 33554500, 2020). "Mutations in XYLT1 were reported in patients with short stature, intellectual disability, flat face and subsequently, XYLT1 mutations were identified in patients with Desbuquois dysplasia type 2 (OMIM #615777)." (PMID 31196143, 2019). "In addition, five XYLT1-mutations were identified in patients suffering from Desbuquois dysplasia type 2, which is defined by pathological ossification." (PMID 25480529, 2014). "Mutations in XYLT1 are implicated in specific genetic disorders, including Desbuquois skeletal dysplasia (DBSD) and Baratela–Scott syndrome." (PMID 39941041, 2025). "For example, deficiencies in XYLT1 and XYLT2, both which encode xylosyl transferases and are involved in the linker synthesis, cause Desbuquois dysplasia type 2 and spondyloocular syndrome, respectively." (PMID 36233030, 2022). "A GGC repeat expansion in the XYLT1 promoter of patients with Baratela–Scott syndrome results in hypermethylation of the first exon and reduced XYLT1 expression." (PMID 32973355, 2021). "Biallelic variants in XYLT1 and XYLT2, encoding xylosyltransferases, are associated with Desbuquois dysplasia type 2 and spondylo-ocular syndrome, respectively." (PMID 31438591, 2019). "Similarly, pathogenic GGC RE in the promoter region of the XYLT1 gene was identified in eight of ten families with Baratela-Scott syndrome (BSS; OMIM: #615777) with single or no causative variants in XYLT1." (PMID 36672937, 2023).
osteoarthritis (6 papers, 2011 to 2023). A noninflammatory degenerative joint disease occurring chiefly in older persons, characterized by degeneration of the articular cartilage, hypertrophy of bone at the margins and changes in the synovial membrane. "Aberrant or suppressed XYLT1 mRNA expression and XT activity have been observed in catabolic PG-associated joint diseases, such as rheumatoid arthritis and osteoarthritis." (PMID 35740472, 2022). "Xylt1 expression increased during the course of chondrogenic differentiation in vitro, and high Xylt serum activity has been linked to osteoarthritis." (PMID 21901110, 2011).
Intellectual disability (3 papers, 2015 to 2020). "Mild to moderate intellectual disability is present in most individuals with mutations in B4GALT7 and all patients with mutations in XYLT1 suffer from a degree of intellectual disability." (PMID 31196143, 2019). "A hypofunctional mutation of XYLT1 encoding xylosyltransferase 1 causes an autosomal recessive short stature syndrome associated with intellectual disability." (PMID 25852466, 2015). "There was also overlap for genes involved in intellectual disabilities, including AFF2, AIFM1, CA8, EEF1A2, MLC1, and XYLT1, but statistically the overlap is not significant." (PMID 32393163, 2020).
spondylo-ocular syndrome (3 papers, 2019 to 2022). Spondylo-ocular syndrome is a very rare association of spinal and ocular manifestations that is characterized by dense cataracts, and retinal detachment along with generalized osteoporosis and platyspondyly. "A gene mutation of XYLT2, the isoform of XYLT1, results in spondylo-ocular syndrome (MIM: 605822), which is characterized by bone fragility, cataracts, and hearing defects." (PMID 36233030, 2022). "Molecular defects in XYLT1 have been associated with Desbuquois dysplasia type 2 (DBQD2) with 28 molecularly proven patients reported hitherto, while XYLT2 mutations cause the so-called spondylo-ocular syndrome (SOS), which has been described in 20 patients thus far." (PMID 31438591, 2019).
autism (2 papers, 2024 to 2025). Persistent deficits in social interaction and communication and interaction as well as a markedly restricted repertoire of activity and interest as well as repetitive patterns of behavior. "Specifically, XYLT1 is highly expressed in the amygdaloid complex, which has been previously implicated in autism and other NDDs." (PMID 40386381, 2025).
dwarfism (2 papers, 2023 to 2025). "For instance, missense mutations in xylosyltransferase 1 (XYLT1) which initiates the addition of GAGs to proteoglycan core proteins, are associated with dwarfism and skeletal abnormalities." (PMID 41278200, 2025).
fibrosis (2 papers, 2020 to 2025). the formation of excess fibrous connective tissue in an organ or tissue in a reparative or reactive process. "We utilized a fibrosis cell culture model established previously and assessed both the direct inhibitor binding to the cellular XT-I protein and the regulation of the XYLT1 transcription and, thus, influencing the corresponding cellular XT activity." (PMID 33096778, 2020). "Consequently, NHDF cells were cultured as a monolayer in a previously established fibrosis cell culture model and treated subsequently with celastrol or amphotericin B in the presence of fibrotic mediator TGF-β1, which had been previously shown to increase the XYLT1 mRNA expression in fibroblasts." (PMID 33096778, 2020).
atherosclerosis (1 paper, 2025). A disease characterized by the build-up of fatty material and calcium deposition in the arterial wall resulting in partial or complete occlusion of the arterial lumen. "Unsupervised DEGs analysis of SMCs revealed increased expression in Abcb8ECKO of TGF-β-pathway genes such as Tgfb1, Tgfb2, Tgfb3, Mmp2 and Col1a1, inflammatory genes such as Ccl2 (encoding for MCP1) and Csf1 as well as atherosclerosis-associated genes including Egr1, Sqstm1, Irf1, Sox4 and Xylt1." (PMID 41252867, 2025).
chondrosarcoma (1 paper, 2018). A malignant cartilaginous matrix-producing mesenchymal neoplasm arising from the bone and soft tissue. "SW1353 chondrosarcoma cells were transfected with miRNA-29b and luciferase plasmids coding for the 3′UTR of XYLT1 to further examine whether miRNA-29b binds directly to the 3′UTR of XYLT1 in vitro." (PMID 30542210, 2018).
Corneal astigmatism (1 paper, 2014). "rs7197218 in the XYLT1 gene, which is related to corneal astigmatism, was genome-wide significant using the cross-sectional data." (PMID 25464127, 2014).
diabetic nephropathy (1 paper, 2014). "This hypothesis is confirmed by the description of only a few SNV, representing risk factors for proteoglycan-associated pathologies like diabetic nephropathy, and two extremely rare, naturally occurring defects in the XYLT1 gene so far." (PMID 25480529, 2014).
glioblastoma (1 paper, 2021). The most malignant astrocytic tumor (WHO grade IV). "More recently, novel xyloside-derived compounds with potential to be used in therapy for glioblastoma were identified due to their ability of impairing endogenous GAG biosynthesis by binding to XYLT1 and β4GAL T7 active sites, and consequently decreasing glioblastoma cell viability." (PMID 34858858, 2021).
linkeropathies (1 paper, 2023). "To date, five genes, encoding various glycosyltransferases, have been linked to linkeropathies; besides the XYLT2 gene, there are the genes XYLT1 (OMIM * 608124), B4GALT7 (OMIM * 604327), B3GAT3 (OMIM * 606374), and B3GALT6 (MIM:* 615291)." (PMID 36833424, 2023).
myopia (1 paper, 2024). "However, further research is still needed to determine the specific mechanism underlying the occurrence of the XYLT1 gene mutation in high myopia." (PMID 39160465, 2024). "According to our research, patients with pathologic myopia had downregulated expression of XYLT1, VCAN, and SPOCK2 and upregulated expression of TUBA1A and EEF1A1." (PMID 39160465, 2024).
ovarian carcinoma (1 paper, 2025). A malignant neoplasm originating from the surface ovarian epithelium. "To determine whether GAG levels affect carboplatin activity, we generated GAG-deficient ES2 ovarian cancer cells using CRISPR-mediated knockout of xylosyltransferases XYLT1 and XYLT2, the enzymes responsible for the initial step in GAG biosynthesis." (PMID 41279644, 2025).
Pseudoxanthoma elasticum (1 paper, 2022). "The suppressive role of CTSB on the expression of XYLT1 was further validated by the quantification of CTSB expression in fibroblasts from patients with the inflammation-associated disease Pseudoxanthoma elasticum." (PMID 35740472, 2022).
skeletal dysplasia (5 papers, 2018 to 2022). Any Mendelian diseases that affects growth and development of the skeleton. "Homozygous and compound heterozygous XYLT1 mutations are known to be causative for skeletal dysplasia, whereby phenotypic characteristics vary concerning severity and include distinct facial abnormalities, joint laxity and short stature." (PMID 35563435, 2022). "In this context, recent studies showed XYLT1 mutations to be causative for the manifestation of skeletal dysplasias, which could at least partially explain the reduced ACAN-expressions observed." (PMID 35563435, 2022). "Mutations in XYLT1 cause skeletal dysplasia and severe growth retardation." (PMID 34837693, 2021). "Expansions in XYLT1 were uncovered using a combination of genome sequencing, microarray analysis, and Sanger sequencing in patients with Baratela-Scott syndrome (BSS), another skeletal dysplasia sharing many clinical features with DBQD2." (PMID 38835438, 2021).
tumor (3 papers, 2015 to 2024). "The expression levels of B3GAT3, XYLT1, XYLT2, B4GALT7, and B3GALT6 were significantly upregulated in OS tissues compared to those in non-tumor tissues, according to the analysis of the bulk RNA-seq dataset (PRJNA539828)." (PMID 38690160, 2024). "We carried out an analysis of XYLT1 protein expression using immunohistochemistry which showed the existence of staining in the normal tissues that could not be detected in experiments performed using non-metastatic tumor samples." (PMID 26482785, 2015).
bone disorder (1 paper, 2025). "Focusing on the role of XYLT1 deficiency during skeletal development using animal models helps us to understand the cellular events leading to the onset of rare human bone disorders." (PMID 40806493, 2025).
XYLT1 also shares sentences with these, for which no sentence is quoted: Desbuquois dysplasia (2 papers); developmental delay (2); Hepatic fibrosis (2); infection (2); systemic sclerosis (2); achondroplasia (1); Arthritis (1); cancer (1); cardiovascular disease (1); colon adenocarcinoma (1); connective tissue diseases (1); Desbuquois dysplasia 2 (1); diabetes (1); fragile X syndrome (1); Friedreich ataxia (1); genetic disorders (1); joint diseases (1); Myocardial fibrosis (1); Obesity (1); polycystic kidney disease (1); rectum adenocarcinoma (1); renal carcinoma (1); schizophrenia (1); scleroderma (1); scoliosis (1).